ESR1 (estrogen receptor 1)
Diseases named in the same sentence as ESR1 in open-access papers (continued):
Sharing a sentence is not in itself a finding about the gene and the disease.
breast cancer (continued). "Compared with female breast cancers (logistic regression), promoter hypermethylation was less common in a variety of genes, particularly ESR1 (P = 0.005), BRCA1 (P = 0.010) and BRCA2 (P < 0.001)." (PMID 22765268, 2012). "The common hub genes between the SRF 50 and Parker breast cancer gene lists were ESR1, MYC, NFkB and ERK1/2." (PMID 22616791, 2012). "Messenger RNA for ER (ESR1) and Ubiquitin C (UbC) were visualized using RNAscope probes and levels were quantified by quantitative in situ hybridization (qISH) on two Yale breast cancer cohorts on tissue microarrays." (PMID 22606272, 2012). "Considering that ESR1 is more significant for breast cancer compared with the other three proteins, overall, Tamoxifen has more of a therapeutic value in Luminal A patients by reversing the gene expression of important disease proteins in the network level." (PMID 23134618, 2012). "Numerous genome-wide association studies (GWAS) also have identified approximately fifty common genetic loci for breast cancer risk in low penetrance genes such as FGFR2, ESR1, LSP1, MAP3K1, RAD51L1 and TOX3." (PMID 22606018, 2012). "In ER+ breast cancers, for both cohorts the ESR1 gene encoding ER alpha (ERα) was the most prominent hub of a large interconnected network, consistent with its central role in this cancer subtype." (PMID 22343619, 2012). "The experiments of ESR1 gene silencing confirmed that the expression of ERα is required for moderate nitrosative stress to increase the proliferative capacity of breast cancer cells." (PMID 23216744, 2012). "Similar to female breast cancer, methylation of ESR1 seems to be a biomarker for high malignant male breast cancer." (PMID 22765268, 2012). "The ascertainments of ESR1_TA, ESR2_CA and AR_CAG in breast cancer have also been of scientific interest, especially on AR_CAG." (PMID 22792352, 2012). "Breast cancers that are “triple-negative” for the clinical markers ESR1, PGR, and HER2 typically belong to the Basal-like molecular subtype." (PMID 23173005, 2012). "The expression of ESR1 is of significant biological and prognostic importance in breast cancer, and largely drives the determination of the management plan." (PMID 22166804, 2012). "Other work also showed that miR-206 expression was reduced in ERα-positive human breast cancer tissues and that miR-206 suppresses ESR1 expression in addition to inhibiting the growth of MCF-7 breast cancer cells." (PMID 23202960, 2012). "The qISH of ESR1 and UbC by this assay was highly reproducible (R2 of 0.86 and 0.79 respectively) on serial sections of a control array with 71 breast cancer cases (YTMA 209) run in 2 independent experiments." (PMID 22606272, 2012). "ESR1 and GSTP1 were the only single genes associated with mitotically active and high-grade male breast cancers." (PMID 22765268, 2012). "We have shown that two SNPs (rs12173570 near ESR1 and rs12371778 near PTHLH) are associated with breast size; these two SNPs have previously been associated with breast cancer risk." (PMID 22747683, 2012). "It has been shown, BARX2 and estrogen receptor-alpha (ESR1) coordinately regulate the production of alternatively spliced ESR1 isoforms and control breast cancer cell growth and invasion." (PMID 22383897, 2012). "SNP rs9383951 is located in intron 5 of the ESR1 gene, an important gene that has been documented to play a key role in breast cancer development and progression." (PMID 22383897, 2012). "In human breast cancer MCF7 cells, treatment with the phthalate BBP led to demethylation of estrogen receptor (ESR1) promoter-associated CpG islands, indicating that altered ESR1 mRNA expression by BBP is due to aberrant DNA methylation." (PMID 22949852, 2012). "This supports our discovery of bimodality of the ESR1 gene expression within the breast cancer samples." (PMID 22053771, 2011).
breast cancer (continued). "One type of genes is bimodal within the breast cancer samples, herein denoted Type 1, with estrogen receptor-alpha (ESR1) having the highest separation." (PMID 22053771, 2011). "Recent studies have indicated that the epigenetic mechanisms that negatively regulate the expression of CXCL12 and ESR1 are involved in breast cancer metastasis and correlate with poor survival of patients." (PMID 22220212, 2011). "ESR1 (estrogen receptor alpha) is a well-known transcription factor involved in the development and progression of breast cancer." (PMID 22053771, 2011). "In fact, in breast cancer cells estrogens activate the Src/Erk pathway through an interaction of the estrogen receptor alpha (ESR1) with the SH2 domain of c-Src." (PMID 21974810, 2011). "In contrast, MCF7 cells represent the luminal A subtype of breast cancer, which retains epithelial markers including ESR1 and E-cadherin." (PMID 21501518, 2011). "Our studies have revealed unexpected relationships in the expression patterns in breast carcinomas between ESR1, C6ORF97 and the two genes immediately upstream (C6ORF211 and C6ORF96 [RMND1])." (PMID 21552322, 2011). "A previous study by our group found a significant difference in serum values of ESR1 and 14-3-3-σ gene promoters between breast cancer patients and healthy controls." (PMID 20487521, 2010). "ESR2 counteracts the activity of ESR1 in many systems and is also expressed in the majority of breast cancers." (PMID 21122099, 2010). "The best established genes with bimodal frequency distributions in breast cancer are the estrogen receptor (ESR1) and erbB2." (PMID 20500820, 2010). "The expression profiles of many of the known breast cancer gene markers such as ESR1, ERBB2 and AR have been shown to follow a strong bimodal distribution, which corresponds to different tumour subtypes." (PMID 21152022, 2010). "While estrogen exposure generally increases the proliferation of ER+ breast cancer cells, in the ER- cell line with re-expression of ESR1 estrogen exposure reduces the proliferation." (PMID 20070909, 2010). "We previously showed that Sin3A is expressed in breast cancer cells and is a repressor of estrogen receptor-alpha (ERα, ESR1) gene expression." (PMID 20920219, 2010). "ESR1 (estrogen receptor 1), a gene frequently silenced in breast cancer, carries 12 predicted miRNA targets, and is downregulated." (PMID 19557174, 2009). "For breast cancer samples, we expect that primary targets of ESR1 will correlate with ESR1 mRNA abundance as protein concentration and mRNA abundance have been shown to associate with cancer sub-types (cf. linear model)." (PMID 19689805, 2009). "ESR1 has been found to be upregulated in Alzheimer's disease and also involved in breast cancer and other complex diseases." (PMID 19779549, 2009). "We selected a panel of three genes, namely, APC, RASSF1A and ESR1, for the detection of tumour-specific methylated DNA in serum samples from healthy controls (n=19) and breast cancer patients (n=79)." (PMID 19367284, 2009). "We selected three genes, namely, APC, RASSF1A and ESR1, which are known to be frequently hypermethylated in breast cancer." (PMID 19367284, 2009). "RASSF1A had the highest frequency of hypermethylation with 35% of breast cancer cases being positive, followed by APC and ESR1 being methylated in 29 and 20% of breast cancer cases, respectively." (PMID 19367284, 2009). "Our results do not support a strong association between common variants in the ESR1 and EGF genes and breast cancer risk, tumour characteristics or survival." (PMID 18271972, 2008). "NCOA3 is the p160 ESR1 transcriptional coactivator and is amplified or overexpressed in breast cancer." (PMID 19007432, 2008). "We sought to determine if common genetic variation in the ESR1 and EGF genes affects breast cancer risk, tumour characteristics or breast cancer survival." (PMID 18271972, 2008).
breast cancer (continued). "We located a region in ESR1 which showed a moderate signal for association with breast cancer risk, but were unable to link common variation in the EGF gene with breast cancer aetiology or prognosis." (PMID 18271972, 2008). "We analysed common genetic variation in the ESR1 and EGF genes in relation to breast cancer risk, tumour characteristics and breast cancer survival using a comprehensive haplotype tagging analysis." (PMID 18271972, 2008). "We selected haplotype-tagging SNPs (tagSNPs) spanning the ESR1 and EGF genomic regions and assessed their association with breast cancer risk, the Nottingham Prognostic Index (NPI) and breast cancer survival." (PMID 18271972, 2008). "We had comprehensive SNP coverage of the entire ESR1 and EGF genes and were thus able to study if there were any common variants in the genes that showed an association with breast cancer risk, NPI or breast cancer survival." (PMID 18271972, 2008). "Nonetheless, other cell lineage-specific transcription factors have been found amplified in cancers, including MITF in melanoma, AR in hormone-independent prostate cancer, ESR1 in breast cancer, and most recently NKX2-1 (TITF) in lung cancer." (PMID 18535672, 2008). "About 70% of breast cancers express oestrogen receptor α (ESR1/ERα) and are oestrogen-dependent for growth." (PMID 17573968, 2007). "Several studies have investigated the associations between polymorphisms in the ESR1 and ESR2 genes and the risk of breast cancer among average-risk women and have reported mixed results." (PMID 16808847, 2006). "The aim of the present study was to analyze the associations between genetic polymorphisms in three estrogen metabolizing enzymes (COMT, CYP1A1, CYP1B1) and the two estrogen receptors (ESR1, ESR2) and the risk of developing breast cancer among women with BBD." (PMID 16808847, 2006). "Moreover, we identified PR-dependent transcriptional programs such as the unfolded protein response (UPR) that can be leveraged to target CSCs in Y537S ESR1-mutant breast cancer." (PMID 41946751, 2026). "Finally, a GR activity signature predicts a good outcome for patients with ER+ breast cancer and anti-correlates with ESR1 expression." (PMID 41261233, 2026). "Remarkably, the viability of MCF-7 D538G cells treated with Dex was reduced more than treatment with vehicle but also more than Fulvestrant (Fig. EV6A), reinforcing the clinical potential of GR activation as an estrogen receptor silencer (ERS) in ESR1 mutant breast cancer." (PMID 41261233, 2026). "Among HER2 + stage I-III (N = 95) and stage IV (N = 78) breast cancers, the most frequent alterations, other than HER2 amplification, were PIK3CA mutations (26% vs 41.0%), followed by BRCA1/2 (6.3% vs 6.4%), ESR1 (1.1% vs 3.9%) mutations, and PD-L1 amplification (1.1% vs 0%)." (PMID 40421962, 2025). "Although direct evidence for its ligand-dependent coregulator function with ESR1 in this disease remains limited, studies in ESR1-positive breast cancers have shown that ZMIZ1 participates in the ESR1 chromatin-bound complex to enhance the expression of cell cycle regulators such as E2F2." (PMID 41321319, 2025). "Prompted by the enhanced activity of the ER+ breast cancer epithelium and elevated ESR1 with age, we assessed cell-specific ESR1 expression and found that it was significantly higher in luminal A and B cancer cells in older patients than those in younger patients." (PMID 41188599, 2025). "The unexpected link between diaphysis BMFF genes and mammary gland development, which involves common associations with ESR1, TNFSF11, and TNFSFR11A, may also relate to such putative BMAT-breast cancer relationships." (PMID 39747859, 2025). "Additionally, in breast cancer, IFN signatures are associated with metastatic disease in specific tumor phenotypes: ESR1+/ERBB2 − tumor metastasis is associated with IFN expression whereas ERBB2 + is not43." (PMID 40894012, 2025).
breast cancer (continued). "Indeed, miRNAs, such as miR‐9, miR‐221, and miR‐222, that directly suppress ESR1 expression, are correlated with the progression of ERα+ breast cancer subtypes." (PMID 39285617, 2025). "Therapeutically, ESR1-targeting agents like Fulvestrant (a SERD effective in breast cancer) may inhibit ESR1-driven TSC signaling in EC." (PMID 40342082, 2025). "ESR1 was not correlated in breast cancer but showed positive associations in rectal, bladder, head and neck, prostate, kidney‐clear cell, glioblastoma, and melanoma." (PMID 40548474, 2025). "Notably, correlation analyses demonstrated a significant positive association between LURAP1L-AS1 and ESR1 expression, suggesting a possible role for LURAP1L-AS1 in ER+ breast cancer." (PMID 39995981, 2025). "This study emphasizes CYP4B1, CYP4F12, and CYP4F3 gene expression levels, presenting tumor versus normal tissue analysis, their expression adjusted by stages, their correlation with BRCA1, BRCA2, and ESR1, the estrogen receptor status, and the overall survival analysis in breast cancer patients." (PMID 40723371, 2025). "Additionally, we observed a significant positive correlation between RAD51B expression and ESR1 downstream target enrichment in human breast cancer cell lines." (PMID 41318657, 2025). "To further investigate the relationship between ESR1 and RPS24 AS, we analyzed transcriptome data from two luminal A-type breast cancer cell lines (MCF7 and T47D) harboring mutations in the ligand-binding domain of the ESR1 gene, a common occurrence in metastatic breast cancer." (PMID 41258078, 2025). "In the breast cancer cell study, interaction between ESR1 and ZMIZ1 to regulate cell cycle progression genes was hypothesized, with demonstrated interactions at the E2F2 gene promoter." (PMID 41321316, 2025). "Thus, this study investigated how AgNPs and nanopolystyrene (PSNPs) interact with oestrogen receptor (ESR1) signalling in breast cancer cells." (PMID 41345200, 2025). "Furthermore, analysis of the TCGA dataset indicated a weak positive correlation between the mRNA levels of SLC7A11 and ESR1 in luminal A and luminal B subtypes of breast cancer." (PMID 39833180, 2025). "In our cell model, ESR1 was markedly upregulated in alpelisib-resistant breast cancer cells." (PMID 40303291, 2025). "In an experimental model of AI-resistant breast cancer, lasofoxifene alone or in combination with palbociclib inhibited tumor growth more than fulvestrant, independent of ESR1 mutation." (PMID 40244377, 2025). "In this pathway, BRCA1 was correlated with the mitogenic action of ESR1 in breast cancer cells." (PMID 40278313, 2025). "There were 227 potential targets of SSD against breast cancer, among which ESR1 was a hub gene." (PMID 40708058, 2025). "ESR1 plays an important role in breast cancer and other estrogen-related diseases." (PMID 40872503, 2025). "Indeed, ESR1 has been identified as a crucial biomarker of metastatic progression in patients with metastatic estrogen receptor-positive breast cancer, which gives a mechanism of resistance in patients treated with aromatase inhibitors." (PMID 40507825, 2025).
breast cancer (continued). "ESR1 is a key protein in the cancer pathway, which is closely associated with the adhesion and migration of tumor cells, and the suppression of EAR1 expression can inhibit the estrogen receptor (ER) breast cancer cells." (PMID 40230723, 2025). "Likewise, the inhibition of ESR1 expression led to suppressed migration and invasion in breast cancer cells." (PMID 41373568, 2025). "Estrogen, a key hormone, plays a pivotal role in driving the progression of breast cancer through its interaction with three receptors: estrogen receptor α (ERα), estrogen receptor β (ERβ), and G-protein coupled estrogen receptor 1 (GPER-1), as well as estrogen-related receptors (ERRs)." (PMID 41200178, 2025). "The ESR1 gene is relevant in breast cancer treatments in the pharmacogenetics context." (PMID 40247433, 2025). "Further, our data suggest that SSD may exert its anti-breast cancer effects via ESR1 and the downstream targets (CCND1 and c-Myc)." (PMID 40708058, 2025). "There are some genetic association studies conducted on Bangladeshi Breast cancer and cervical cancer population to evaluate susceptible single nucleotide polymorphisms of INSIG2, HLA-DRB1, GCNT1P5, IL1β, IL4R, IL6, FGFR2, CYP1A1, ESR1 genes and disease outcome." (PMID 40920780, 2025). "Finally, we determined the role of estrogen receptor in the observed increase of stem-like properties by silencing ESR1 in breast cancer cells." (PMID 39349458, 2024). "Moreover, a previous study demonstrated that CCDC170 wasfused to ESR1 in breast cancer (Veeraraghavan etal., 2014)." (PMID 38626574, 2024). "In addition, the miRNA-221/222 cluster has been shown to induce EMT in breast cancer cells by targeting Dicer, and estrogen receptor 1 (ESR1)." (PMID 38540304, 2024). "Further investigation of ESR1 mutant in a clinical breast cancer cohort (SCAN-B31; n cases = 27; n controls = 108, see Methods for details) largely confirmed our cell model results (top enriched pathways: E2F targets, G2M checkpoint, MYC targets, and mTORC1 signaling)." (PMID 38519482, 2024). "Key molecular biomarkers such as estrogen receptor (ER), progesterone receptor (PR), and human epidermal growth factor receptor 2 (HER2) drive treatment decisions in primary breast cancer, and mutations in genes like ESR1, PIK3CA, BRCA1, and BRCA2 inform personalized therapies." (PMID 39335124, 2024). "In WT ESR1 breast cancer cells, T6I-29-1A uniquely impacted genes related to SUMOylation." (PMID 38978585, 2024). "Interestingly, we found that the BrC12 contains ESR1, which is the target of endocrine therapy of HR+ breast cancer." (PMID 38622359, 2024). "Preoperative ESR1 mRNA therapy in cases with an advanced stage of ER-negative or TNBC-type breast cancer may result in an obvious tumor response coupled with stimulated immune-competent cells in the neighboring tissues." (PMID 39329990, 2024). "Estrogen receptor 1 (ESR1) is primarily expressed in breast cancer and promotes metastasis." (PMID 39327445, 2024). "While neoantigen load is predictive of T-cell infiltration in multiple cancers, including breast cancer, Williams and colleagues found that ESR1 mutations did not increase endogenous CD8+ T-cell infiltration." (PMID 38335301, 2024). "In breast cancer patients, the ESR1 gene expression was found to indicate a positive ER status." (PMID 39202273, 2024). "OP-1250 is a bioavailable CERAN demonstrated in ESR1 mutant breast cancers." (PMID 39063972, 2024). "Indeed, a study found that in 41% of primary breast cancer tumours investigated, the promoter of the ESR1 gene was hypermethylated, which strongly correlated with reduced ERα protein expression and more advanced disease." (PMID 39282472, 2024).